HECA (HECA ribonucleoprotein granule regulator)
Description:
May play an important role in some human cancers. May be part of the regulatory mechanism in the development of epithelial tube networks such as the circulatory system and lungs.
Synonyms: hHDC; HDC; HDCL; dJ225E12.1
Tractability: PROTAC: ubiquitination databases record sites on it; its protein half-life has been measured.
Gene: Protein-coding gene on chromosome 6 (139,135,080 to 139,180,807, forward strand). Ensembl gene ENSG00000112406.
Subcellular location (Human Protein Atlas): Cytosol
Gene Ontology:
Molecular function: RNA binding
Biological process: negative regulation of mitotic cell cycle; stress granule assembly; respiratory tube development
Cellular component: cytoplasm; cytoplasmic stress granule; membrane; nucleus
Genetic constraint (gnomAD): Loss-of-function variants: 12 observed, 33.65 expected, observed/expected ratio (o/e) 0.36, 90% interval 0.23 to 0.58. The upper end of that interval is the gene's LOEUF score, 0.58, which puts it in group 2 of 6, group 1 being the genes least tolerant of losing a copy. Missense variants: 423 observed, 584.7 expected, observed/expected ratio (o/e) 0.72, 90% interval 0.67 to 0.78. Synonymous variants: 238 observed, 240.83 expected, observed/expected ratio (o/e) 0.99, 90% interval 0.89 to 1.1.
Homologues: Orthologues: macaque HECA (99% identical), dog HECA (97% identical), pig HECA (96% identical), mouse Heca (96% identical), rat Heca (96% identical), chimpanzee HECA (90% identical), guinea pig HECA (81% identical), zebrafish heca (70% identical), tropical clawed frog heca (65% identical), Drosophila melanogaster heca (33% identical), Caenorhabditis elegans cri-1 (19% identical), Caenorhabditis elegans B0238.9 (18% identical).
Diseases named in the same sentence as HECA in open-access papers:
HECA is named in the same sentence as 10 diseases in open-access papers, as found by Europe PMC text mining. Sharing a sentence is not in itself a finding about the gene and the disease. The quoted sentences say what the papers report.
oral squamous cell carcinoma (2 papers, 2017 to 2022). "Studies on oral squamous cell carcinoma have shown that the HECA promoter is a target of the Wnt/β‐catenin pathway and that HECA protein antagonizes Wnt/β‐catenin pathway‐mediated cell proliferation." (PMID 35949005, 2022).
atrial septal defect (1 paper, 2022). Interauricular communication is a congenital malformation characterized by a communication between the atrial chambers of the heart. "In this study, we identified a candidate gene, HECA, by whole‐exome sequencing of an atrial septal defect family." (PMID 35949005, 2022). "To confirm the role of HECA in CHD, we performed whole‐exome sequencing (WES) in a family with atrial septal defect (ASD) and 689 patients with sporadic CHD, and analyzed the association of rare variants of HECA with CHD risk." (PMID 35949005, 2022).
breast carcinoma (1 paper, 2013). "Among these genes, NRIP1, HECA and FIS1 were of particular interest because they have previously been reported to be associated with breast cancer pathogenesis, and further studies of these genes will be pursued." (PMID 24355041, 2013). "Among these genes, NRIP1, HECA and FIS1 were of particular interest since they have previously been reported to be associated with breast cancer pathogenesis." (PMID 24355041, 2013).
panic disorder (1 paper, 2022). An anxiety disorder characterized by multiple unexpected panic attacks with persistent concern of recurring attacks. "In several EWAS studies of panic disorder, it was found that 40 CpG loci were significantly associated with hypo-methylation, gender-specific methylation changes may exist in HECA gene, and the degree of cg19917903 methylation in CFAP46 gene decreased significantly." (PMID 36032246, 2022).
tumor (3 papers, 2012 to 2024). "We also observed that HECA deficiency in AC16 cells promoted cell migration, which differed from findings in tumor cells." (PMID 35949005, 2022). "Since the human orthologue of Hdc, HECA, was shown to be a tumor suppressor in several tumor models, our results on how Hdc regulates progenitor differentiation in Drosophila may implicate mechanisms potentially relevant in combating HECA-related cancer types." (PMID 39466810, 2024). "However, we do not discount the possible existence of Mac-2BP glycoforms lacking HECA-452 mAb reactivity, especially because some fraction of Mac-2BP expressed in tumor tissue was not reactive to HECA-452 mAb." (PMID 22970241, 2012).
HECA also shares sentences with these, for which no sentence is quoted: cancer (2 papers); congenital heart disease (1); glioma (1); retinal degeneration (1); Sepsis (1).